CD40 (CD40 molecule)
Diseases named in the same sentence as CD40 in open-access papers (continued):
Sharing a sentence is not in itself a finding about the gene and the disease.
parasitemia (9 papers, 2013 to 2024). "These B cells responded differentially to parasite infection and a previous report supports this finding by showing that PerC B cells activated by anti-CD40 and LPS secreted more IL-10 and IL-6 compared to splenic B cells." (PMID 32197642, 2020). "Although CD40-induced STING upregulation leads to reduced CD40 levels and thus downstream NF-κB signalling, type I interferon immunity has been suggested to be highly inducible in certain strains of parasitic infection." (PMID 28596706, 2017). "In another lethal model of P. berghei ANKA/C57BL/6 mice, host mortality was greatly decreased in CD40-/- and CD40L-/- mice after infection with the parasite, even though parasitemia were similar in the WT, CD40-/- or CD40L-/- mice." (PMID 27716849, 2016). "The WT and CD40 KO mice also had similar parasitemia after day 8, but the CD40 KO mice died earlier." (PMID 27716849, 2016). "C57BL/6 mice infected with N67 parasite induced a strong IFN-I response, including increased expression of genes such as Cd40, Isg15, Isg20, Ifit2, Mx1, Mx2, Ddx58, and Usp18 genes, leading to suppression of N67 parasitemia." (PMID 27716849, 2016). "Given the importance of CD40 in coordinating adaptive immune responses, it has been well studied in the context of the activation and recruitment of B- and T-cells that are critical for controlling a variety of chronic bacterial and parasitic infections." (PMID 37376652, 2023). "The mutations in the TRAF binding domains also affect STING protein level, consistent with the observations showing increased CD40 and STING proteins after co-transfection of plasmids containing genes encoding both molecules and decreased STING protein in CD40-/- mice after parasite infection." (PMID 27716849, 2016). "As expected, the day 2 (24 h after parasite injection) serum levels of IFN-β were significantly lower in the CD40-/- mice than those of WT mice after parasite infection; however, the IFN-β level quickly returned to low levels despite continuous increase of parasitemia." (PMID 27716849, 2016). "In addition to protection against viral and bacterial infections, CD40 also contributes to protection against parasitic infections such as Trypanosoma cruzi, Leishmania amazonensis, and Plasmodium yoelii." (PMID 27716849, 2016). "The relatively high MHCII expression on their surface and the upregulation of APC marker genes including CD83, CD40, and B7-H1 is somewhat surprising since in mammals granulocytes are typically, short-lived effector cells involved in clearance of bacterial and parasitic infections." (PMID 23761795, 2013). "In the P. berghei ANKA/C57BL/6 model, better survival rates were found in CD40-/- and CD40L-/- mice after infection with the parasite, despite similar parasitemia in the WT, CD40-/- or CD40L-/- mice." (PMID 27716849, 2016). "Using a Plasmodium yoelii nigeriensis N67 and C57BL/6 mouse model, we showed that infected CD40-/- mice had reduced STING and serum IFN-β levels day-2 post infection, higher day-4 parasitemia, and earlier deaths." (PMID 27716849, 2016). "To investigate the role of CD40 in IFN-I mediated protection against malaria infection, we infected wild type (WT) and CD40-/- mice with N67 and monitored parasitemia and host mortality." (PMID 27716849, 2016). "In addition, CD40 is important in the IFN-I response, parasitemia control, and host survival, and its signaling in macrophages inhibit acute viral replication at the early stages of infection." (PMID 36045684, 2022). "Therefore, increased STING expression may dampen CD40 mediated inflammatory responses and damage to the host, while promoting a strong IFN-I response to control parasitemia." (PMID 27716849, 2016).
Allergy (8 papers, 2018 to 2023). An allergy is an immune response or reaction to substances that are usually not harmful. "Moreover, CD40 is implicated in lower airway diseases, especially in allergy." (PMID 33976586, 2021). "In other studies, we demonstrated that ex vivo silencing of CD40 in DCs can ameliorate RA and allergic diseases." (PMID 30949517, 2019). "DCs as antigen-presenting cells participate in allergies by expressing B220 and CD40." (PMID 35804699, 2022). "CD40-silenced DCs have been shown to suppress OVA-induced allergy." (PMID 33976586, 2021). "Notably, neither 24 nor 48 hours of co‐incubation of MA::Art v 1 VNP, Art v 1::GPI VNP, empty VNP (10 μg/mL each), or rArt v 1 protein (1 μg/mL) with bone marrow‐derived dendritic cells (BMDC) of TCR/DR1 allergy mice upregulated CD40, CD80, CD86, or MHC class II expression, when compared to medium." (PMID 30035810, 2019).
Insulin resistance (8 papers, 2017 to 2025). Increased resistance towards insulin, that is, diminished effectiveness of insulin in reducing blood glucose levels. "In contrast, genetic deficiency of CD40 resulted in a worsened metabolic phenotype with increased insulin resistance (IR), exacerbated adipose tissue inflammation and liver steatosis." (PMID 30096208, 2018). "In contrast to the CD40L knockout model, global CD40 knockout aggravates inflammation and insulin resistance in obese mice." (PMID 39899926, 2025). "Unexpectedly, absence of CD40 worsened insulin resistance and caused excessive adipose tissue inflammation and hepatosteatosis." (PMID 30096208, 2018).
liver disease (8 papers, 2007 to 2023). "Surprisingly, coadministration of an agonistic anti-CD40 antibody (αCD40) inhibited PD-1 induction and restored T cell effector function, thereby inhibiting viral gene expression and causing a necroinflammatory liver disease." (PMID 23853599, 2013). "In anti-CD40 mAb-induced necro-inflammatory liver disease, the importance of TNF-α has been emphasized." (PMID 34440067, 2021). "We found that acute PHZ-induced hemolysis leads to an increase in intracellular heme in macrophages, which profoundly suppressed macrophage-driven inflammatory liver disease induced by an agonistic anti-CD40 antibody." (PMID 34054870, 2021). "In the present study, the wt mice revealed necro-inflammatory liver disease upon CD40 activation with pronounced areas of hepatocellular necrosis and inflammatory cell accumulation." (PMID 34440067, 2021). "Cryptosporidium species was identified in only 2 cases, one of whom had cholangitis and liver disease, which is normally associated with MHC class II or IL-21/IL-21 receptor deficiencies but also described in CD40 ligand and CD40 deficiency." (PMID 27555459, 2017). "HBV-specific CD8+ T cells differentiated into fully functional effector T cells in recipient HBV transgenic mice that were treated with agonistic anti-CD40 antibodies (αCD40), resulting in liver disease and the inhibition of HBV gene expression." (PMID 23853599, 2013). "Whilst constitutive expression of CD40 is low in the liver during normal circumstances, it is widespread and increased during inflammatory liver disease implying that it has a pivotal role in regulation of host responses to injury." (PMID 17225862, 2007). "Notably, the dataset includes many known proteins (IL6, IL10, IFNG, CSF3, PDGFB, CD40, and AFP) and novel proteins associated with liver diseases." (PMID 37209815, 2023). "This led us to believe that heme could be the key driver of macrophage suppression, resulting in protection from anti-CD40-induced inflammatory liver disease." (PMID 34054870, 2021). "Therefore, increased CD40 implies that various immune responses occur in liver disease." (PMID 24337678, 2014). "Furthermore, both CD40 and ICAM-1 contribute to the inflammatory reaction and fibrosis generation in progressive liver disease." (PMID 24337678, 2014).
metabolic syndrome (8 papers, 2018 to 2024). A cluster of metabolic risk factors for CARDIOVASCULAR DISEASES and TYPE 2 DIABETES MELLITUS. "Similar results were observed in an obese mouse model, in which CD40 depletion increased the inflammation in adipose tissue, increasing body weight and contributing to the development of metabolic syndrome." (PMID 36297185, 2022). "For instance, metabolic syndrome was worsened and hepatic inflammation ameliorated upon depletion of CD40 on CD11c+ in a model of dietary non-alcoholic steatohepatitis." (PMID 34440067, 2021). "We investigated the role of CD40+CD11c+ cells in the metabolic syndrome and nonalcoholic steatohepatitis (NASH)." (PMID 31604965, 2019). "Our experiments suggest that CD40 expressing CD11c+ cells can act as a double-edged sword: CD40 expressing CD11c+ cells contribute to liver inflammation during NASH but are protective against the metabolic syndrome via induction of regulatory T cells." (PMID 31604965, 2019). "While genetic ablation of CD40L ameliorates the metabolic syndrome, CD40-/- mice have an unexpected worsened obese phenotype." (PMID 30096208, 2018).
metastatic disease (8 papers, 2012 to 2025). "Another intriguing finding is the association of CD40 expression in TILs and in CAFs with the development of metastatic disease (adrenal glands, brain and liver)." (PMID 31137630, 2019). "CD40 stimulation and IL-2 synergize to induce complete regression of metastatic tumors due to potentiation of T cell survival and CD40 expression of DCs, stimulating an immunomodulatory cascade." (PMID 35582441, 2020). "We have previously shown that immunotherapy using agonist CD40 antibodies combined with high doses recombinant human IL-2 results in synergistic anti-tumor responses against metastatic disease in tumor bearing mice." (PMID 23133545, 2012). "The observed response in the untreated tumor has also been observed for other cancers with anti-CD40 administered in situ and may be attributed to levels of immunosuppression in primary and metastatic tumor environments." (PMID 32331490, 2020). "If the approach to use SRBs loaded with CD40 mAb to boost the abscopal effect is translated clinically, this could transform RT practice, extending the use of RT to the treatment of both local and metastatic tumors." (PMID 29594038, 2018). "High CD40 RNA levels were not prognostic for overall survival (OS) from metastatic disease (P = 0.2) (n = 272 immune checkpoint inhibitor (ICI)-naïve patients)." (PMID 41182434, 2025). "Among those who never received immunotherapy, the median OS from advanced/metastatic disease was 63.3 months (95% CI, 33.7–Not available [NA]) in the high-CD40 group and 42.2 months (95% CI, 30.1–46.2) in the low-CD40 group (P = 0.16)." (PMID 41182434, 2025). "Surprisingly, complete dLN resection did not alter lung metastatic disease survival frequency for either aCTLA4 or aPD-1/CD40 treatment." (PMID 33835222, 2021).
primary immunodeficiency (8 papers, 2014 to 2025). "X-linked hyper-IgM syndrome (XHIGM) is one type of primary immunodeficiency diseases, resulting from defects in the CD40 ligand/CD40 signaling pathways." (PMID 25215306, 2014). "Because of epigenetic controls on primary immunodeficiency and NF-κB signaling pathway modulation, we used ChIP-qPCR to detect histone mark enrichments in the CD40 and ZAP70 genes." (PMID 40005847, 2025). "The IPA pathway analysis of DEGs for the TME regions in KRASmut showed that their DEGs were enriched in the TME, primary immunodeficiency and CD40 signaling pathways with a p-value < 0.001." (PMID 36831441, 2023). "In particular, mutations in CD40LG, CD40, AICDA, or UNG cause hyper-IgM (HIGM) syndrome, a heterogeneous group of primary immunodeficiencies." (PMID 30131802, 2018). "In addition, related primary immunodeficiency and NF-κB signaling pathway genes such as CD40 and ZAP70 significantly increase after MLT treatments in cIECs, which is in accordance with the previous study." (PMID 40005847, 2025). "Malfunctions in the process of CSR may result in the development of primary immunodeficiency diseases (PID), such as HIGM, which is attributed to mutations in BCR or coreceptor signaling components (such as CD19 or CD40)." (PMID 39144468, 2024).
ulcerative colitis (8 papers, 2010 to 2025). An inflammatory bowel disease involving the mucosal surface of the large intestine and rectum. "Furthermore, B cell expression of CD40 is also required for protection in models of collagen-induced arthritis, ulcerative colitis, EAE, and salmonella infection." (PMID 35046933, 2021).
depression (7 papers, 2021 to 2026). "A previous study suggested that newly diagnosed depression is associated with increased expression of platelet-derived CD40." (PMID 38297317, 2024). "In mice, CD40 activation leads to sickness behavior syndrome (SBS) comprising weight loss, sleep disruption and depression, which can be blocked by administration of the TNF-inhibitor etanercept." (PMID 34440067, 2021).
ischemic stroke (7 papers, 2017 to 2025). A stroke disorder caused by obstruction of blood flow to the brain, due to thrombotic (local blood clot formation) or embolic (due to a blood clot or other material traveling from another site) event. "The PPI network analysis revealed significant associations between PARP1, MCL1, and CD40, highlighting potential common pathways involved in ischemic stroke, epilepsy, and VaD." (PMID 40624693, 2025). "Distribution of the genotype and allele frequencies four polymorphisms ofthe CD40 gene in ischemic stroke (IS) patients and control subjects." (PMID 28590502, 2017). "CD40 activation has been shown to contribute to inflammation, which is a key factor in the pathogenesis of ischemic stroke." (PMID 40624693, 2025). "In thisstudy, we investigated the association of four polymorphisms (rs1883832, rs13040307,rs752118 and rs3765459) of CD40 gene and their effect on CD40 expression with therisk of ischemic stroke (IS) in a Chinese population." (PMID 28590502, 2017). "Furthermore, the interaction between MCL1 and CD40—a co-stimulatory protein involved in immune responses—indicates a link between apoptotic regulation and immune modulation in the context of ischemic stroke." (PMID 40624693, 2025). "Furthermore, recent studies have reported TWEAK, matrix metallopeptidase 12, CD40, and scavenger receptor class A member 5 as promising targets for the treatment of ischemic stroke." (PMID 33263724, 2021). "Additionally, inflammation peaks 24–72 hr after ischemic stroke, and our data support this with increased CD40+ macrophages at these time points." (PMID 28523230, 2017).
Opportunistic infection (7 papers, 2010 to 2025). An infection that is caused by a pathogen that would generally not be able to cause an infection in a host with a normal immune system. "Clinically, CD40 deficiency is characterized by defects in cellular and humoral immunity resulting in a susceptibility to recurrent sinopulmonary bacterial infections and severe opportunistic infections." (PMID 37515027, 2023). "In addition, global inhibition of CD40 signalling will cause immunosuppression and susceptibility to opportunistic infections." (PMID 35920844, 2022). "Since the CD40/CD40L pathway also mediates co-stimulation between activated CD4+ T cells and CD40-expressing monocytes, macrophages, and dendritic cells, mutations in either CD40L (X-linked) or in CD40 (AR) also lead to opportunistic infections, notably Pjp." (PMID 36986378, 2023). "Whereas, deficiencies in the CD40L/CD40 and NF-kB pathways are characterized by opportunistic infections, patients with defects in AID and UNG generally do not experience such complications." (PMID 30319630, 2018). "Identification of how CD40 triggers this cascade may enable development of a novel approach to disrupt CD40 without inducing thrombosis or increasing susceptibility to opportunistic infections." (PMID 35920844, 2022). "For instance, the lack of proper interaction between T lymphocytes and monocytes in CD40/CD40L deficiencies confers an increased risk for Pneumocystis jiroveci pneumonia, an opportunistic infection not frequent in others CSR/HIGM defects." (PMID 30319630, 2018).
osteosarcoma (7 papers, 2018 to 2024). A usually aggressive malignant bone-forming mesenchymal neoplasm, predominantly affecting adolescents and young adults. "Inhibition of MYC reprograms TME by recruiting T lymphocytes and activating the CD40/CD40L system in osteosarcoma." (PMID 36106335, 2022). "Previous studies have also found that CD44, CD40, PDCD1LG2, LAG3, and HAVCR2 can be immunotherapeutic targets for osteosarcoma." (PMID 38071320, 2023). "Taken together, these data indicated that c-Myc inhibition can upregulate CD40/CD40L expression and induce T cell infiltration and activation in osteosarcoma." (PMID 35292660, 2022). "Furthermore, several immune molecules, such as cytotoxic T cell lymphocyte antigen 4 (CTLA4) and CD40 (TNF receptor superfamily 5), have been targeted clinically in osteosarcoma." (PMID 29720180, 2018). "In the JQ-1 treatment group, the positive signals of CD40 and CD40L were not only increased but also showed mutual proximity and interactions at many locations inside the tumors, suggesting that c-Myc inhibition can enhance the CD40-CD40L interaction in the osteosarcoma microenvironment." (PMID 35292660, 2022).
schizophrenia (7 papers, 2020 to 2026). A major psychotic disorder characterized by abnormalities in the perception or expression of reality. "Similarly, CD40 expression in brain may influence risk of both schizophrenia and bipolar disorder by causally influencing psychotic symptoms, which are common to both conditions." (PMID 40281223, 2025). "AGER (Tier A evidence for schizophrenia) and CD40 (Tier B evidence for both schizophrenia and bipolar disorder) have drugs in advanced clinical trials." (PMID 40281223, 2025). "One transcriptional change in Shn2 KO cortex that was opposite to what we found in high neuroinflammation schizophrenia cortex was downregulation of CD40 mRNA." (PMID 32680547, 2020). "Among them, AGER (schizophrenia), CD40 (schizophrenia & bipolar), TNFRSF17 (schizophrenia), ACE (schizophrenia & Alzheimer’s) and SEPRING1 (schizophrenia) have drugs approved or in advanced clinical trials for several indications including cardiovascular and autoimmune conditions." (PMID 40281223, 2025). "Given other findings indicative of microglial suppression in schizophrenia, it is likely that cortical upregulation of the CD40 transcript in high neuroinflammation schizophrenia is driven by non-microglial cells that also express CD40." (PMID 32680547, 2020).
type 2 diabetes (7 papers, 2011 to 2024). "CD40-rs1126935 too was associated with MAS with coma in more than one site." (PMID 23614351, 2013). "Activation of microglial CD40 results in inflammation-induced seizures and underpins the association between this polymorphism and MAS in coma/cerebral malaria." (PMID 23614351, 2013). "Here we report that adults with type 2 diabetes have significantly up-regulated surface expression of CD40 and CD80 with a lag of 2 and 3 days and significantly elevated CD86, HLA-DR, and CD23 expression at a lag of 4 days on circulating monocytes." (PMID 21169129, 2011). "In contrast to healthy subjects, most regular consumption trials with patients suffering from type 2 diabetes or impaired glucose tolerance found lower concentrations of ICAM-1 and P-selectin in serum or plasma and a reduced expression of VLA-4, CD36, and CD40 on monocytes." (PMID 27240397, 2016).